LINC01600 (long independently transcribed non-coding RNA 1600)
Synonyms: C6orf195; FLJ31934; bA145H9.2
Gene: Long non-coding RNA gene on chromosome 6 (2,562,085 to 2,634,734, reverse strand). Ensembl gene ENSG00000164385.
Diseases named in the same sentence as LINC01600 in open-access papers:
LINC01600 is named in the same sentence as 4 diseases in open-access papers, as found by Europe PMC text mining. Sharing a sentence is not in itself a finding about the gene and the disease. The quoted sentences say what the papers report.
lung adenocarcinoma (2 papers, 2020 to 2023). A carcinoma that arises from the lung and is characterized by the presence of malignant glandular epithelial cells. "The previous study indicates that LINC01600 is upregulated in lung adenocarcinoma (LUAD) and its promoter and enhancer show increased activity in luciferase reporter assays." (PMID 32318351, 2020).
colorectal cancer (1 paper, 2020). A primary or metastatic malignant neoplasm that affects the colon or rectum. "Besides, it has been shown that various lncRNAs such as MIR22HG and LINC01600 play an important role in colorectal cancer." (PMID 33194594, 2020).
cancer (2 papers, 2017 to 2022). A tumor composed of atypical neoplastic, often pleomorphic cells that invade other tissues. "EIF2S2 activated the Wnt signaling pathways to drive cancer development by regulating the interaction of LINC01600 with Myc protein." (PMID 35669725, 2022). "LINC01600 is an intergenic non-protein coding RNA, and very few studies have investigated its role in cancers." (PMID 27903974, 2017).
tumor (1 paper, 2020). "RT-qPCR was used to detect the expression of LINC01600, JUND, ZFP36, and ATF3 in tumor tissues of 40 PCa patients collected in our hospital." (PMID 32318351, 2020).